PPARG (peroxisome proliferator activated receptor gamma)
Diseases named in the same sentence as PPARG in open-access papers (continued):
Sharing a sentence is not in itself a finding about the gene and the disease.
psoriasis (continued). "We identified 5 STFs (PPARG, ZFPM2, ZNF415, HLX, and ANHX) in common DEGs and investigated their potential roles in psoriasis and AD." (PMID 35669784, 2022). "Many other studies have reported that the protein expression levels of PPARG, MMP9, and MYC were also strongly correlated with the incidence of psoriasis." (PMID 35265149, 2022). "In lesional skin of patients with psoriasis and atopic dermatitis the expression of PPARD was also increased while the expression of PPARA and PPARG was decreased." (PMID 21573029, 2011). "Additionally, ZNF384 was identified as the key transcription factor that modulates the expression of PPARG, ZNF415, HLX, and ANHX, pointing to its potential as a therapeutic target for psoriasis and AD." (PMID 40343299, 2025). "PPARG, ZFPM2, ZNF415, and HLX were down-regulated in psoriasis and AD, while ANHX was up-regulated." (PMID 40343299, 2025). "The STFs (PPARG, ZFPM2, ZNF415, HLX, and ANHX) may increase the morbidity rate of AD in psoriasis by initiating a positive feedback loop of excessive inflammation and metabolic disorders." (PMID 35669784, 2022). "PPAR-γ inhibits the transcription of IL-17 by inhibiting its direct transcription factors RORC and STAT3, while FRA-1 can regulate the expression of STATA3, RORC and IL-17 by directly inhibiting PPARγ, thus regulating the development of psoriasis." (PMID 36032067, 2022). "In this work, to test the hypothesis of low activity of PPARγ signaling in psoriasis, we measured gene expression of PPARγ and several key members of the reconstructed model in skin samples and in CD3+ T cells from patients with psoriasis." (PMID 34445309, 2021). "Regarding the candidate targets, estrogen receptor (ESR1) showed the highest degree (113°), followed by PTGS2 (86°), NOS2 (81°), PPARG (60°), and GSK3B (56°), which demonstrated the potential therapeutic effect of each drug in LXJD formula for ameliorating psoriasis." (PMID 34168554, 2021). "There is no experimental evidence about PPARγ activity level in human skin of patients with psoriasis to our knowledge." (PMID 33133175, 2020). "Since PPAR β/δ may act as a direct antagonist to PPARγ and PPARγ activation inhibits STAT3, activation of PPARγ unsurprisingly has a mild inhibitory effect on psoriasis." (PMID 22606335, 2012). "A proapoptotic effect of PPARγ in T cells has been observed, and activation of PPARγ has an inhibitory effect on psoriasis, whereas this is not the case with PPARβ/δ activation." (PMID 20706605, 2010). "We have found that two other drugs (calcitriol and paclitaxel) that indeed reduce inflammation in psoriasis, however, may not be very effective in psoriasis treatment because they inhibit PPARγ or FOXP3." (PMID 34445309, 2021). "It is not clear what upstream pathway is the most important for PPARγ/IL17 regulation in psoriasis." (PMID 34445309, 2021). "This review summarizes mechanistic insights into PPARγ-driven FAO and SCFA-mediated immunomodulation, proposing novel metabolic and microbiome-targeted strategies for psoriasis treatment." (PMID 41868135, 2026).
coronary artery disease (44 papers, 2008 to 2025). "The T allele of the PPARγ exon 6 C161T polymorphism was supposed to have protective role against coronary artery disease in Chinese population, whereas others found that this allele was associated with an increased risk for coronary heart disease." (PMID 28781590, 2017). "Recently, another study showed that PPARγ gene C161→T substitution was associated with reduced risk of coronary artery disease through modulation of pro-inflammatory cytokines, MMP-9 and TNF-α expression in a Chinese population." (PMID 20334678, 2010). "We were unable to reproduce a previously found interaction between PPARγ Pro12Ala and overweight in relation to coronary heart disease, where it was found that the variant allele was a stronger risk factor among overweight men and women." (PMID 19500413, 2009). "Therefore, the persistent cellular infiltration of the adventitia of aneurysms was associated with an increased M-CSF and PPARγ expression, while the aorta of patients with coronary artery disease showed higher level of chemokine CCL2 and cytokine IL-6." (PMID 26539497, 2015). "PPARγ C161→T substitution is associated with a reduced risk of coronary artery disease (CAD)." (PMID 20334678, 2010). "In aorta, we identified perturbations in a number of TFs involved in circadian clock regulation (CRY1, CRY2, PER2), vascular inflammation (PPARG, NR3C1), and those linked in coronary artery disease, including the estrogen receptor, ESR2." (PMID 39896461, 2025). "Further cellular experimental validation proved that FC treatment decreased the expression of PPARg, thus alleviated coronary artery disease by attenuating hypoxia-reoxygenation injury." (PMID 41515139, 2025). "Flavonoid has been demonstrated to exert a cardioprotective effect in ischemic heart disease in diabetic rats by activating PPARγ signaling and reducing left ventricular end-diastolic pressure and mean arterial pressure in diabetic rats." (PMID 36815021, 2023). "Peroxisome proliferator-activated receptor γ (PPARγ) activation significantly decreases arterial stiffness and inflammation in diabetic patients with coronary artery disease." (PMID 33781257, 2021). "Experimental studies investigating a possible therapeutical potential for PPARγ agonists in ischemic heart disease started in 2001 with a report from Eliot H. Ohlstein’s group." (PMID 33322384, 2020). "We assessed the relationship between 4 PPARG SNPs (C-681G, C-689T, Pro12Ala, and C1431T) and coronary heart disease (CHD) in the PRIME (249 cases/494 controls, only men) and ADVANCE (1,076 cases/805 controls, men or women) studies." (PMID 20016803, 2009). "Our results are in accordance with previous studies reporting the anti-inflammatory actions of pioglitazone in coronary arteriosclerosis by reducing the expression of CCL2 receptor (CCR2) as well as in traumatic brain injury by modulating the PPARγ/NF-κB/IL-6 pathway." (PMID 37958504, 2023). "Zhishi Xiebai Guizhi Decoction may play a role in treating coronary heart disease by activating PPARγ." (PMID 34966435, 2021). "Treatment with the PPARγ agonists rosiglitazone and pioglitazone has been shown to significantly decrease arterial stiffness and arterial inflammation in diabetic patients with coronary artery disease, as well as in obese glucose-tolerant patients." (PMID 33781257, 2021). "Pioglitazone, a peroxisome proliferator-activated receptor gamma or PPARγ agonist, was shown to prevent ischemia-induced ED in healthy subjects, and improve endothelial and adipose tissue dysfunction in pre-diabetic patients with coronary artery disease (CAD)." (PMID 28750629, 2017). "However, in UK and Chinese individuals with coronary artery disease (CAD), the PPARγ C1431T polymorphism is significantly associated with CVD risk factors, such as fasting serum lipid profiles, in the context of variant genotypes (CT + TT)." (PMID 28042289, 2016).
coronary artery disease (continued). "The aim of study was to find the correlation between PPARγ expression during development of HF in patients with coronary artery disease (CAD) after coronary artery bypass grafting (CABG)." (PMID 25371662, 2014). "The aim of study was to find the correlation between PPARγ expression during development of HF in patients and coronary artery disease (CAD) after coronary artery bypass-grafting (CABG)." (PMID 25371662, 2014). "Fructus Choerospondiatis (FC) components were found to regulate the PPAR signaling pathway, indicating a potential relationship between PPARG and AKT1 in the treatment of coronary heart disease." (PMID 38505269, 2024).
lipid metabolism disorders (44 papers, 2016 to 2026). "DEHP causes lipid metabolism disorders by activating the PPARα or PPARγ signal transducer and farnesoid X receptor or liver X receptor signaling pathway, respectively." (PMID 35778735, 2022). "PPARγ can enhance lipid accumulation in adipocytes, thereby causing lipid metabolism disorders, such as elevated TG levels and reduced high-density lipoprotein cholesterol (HDL-C) levels." (PMID 33180852, 2020). "In summary, these findings clearly highlight the value of PPARα and PPARγ as key therapeutic targets for regulating renal lipid metabolism disorders in DKD." (PMID 41170356, 2025). "Specifically, activating PPARγ is the “core switch” for Sch B to improve lipid metabolism disorders." (PMID 41155555, 2025). "Studies have confirmed that BBR can improve lipid metabolism disorders by regulating PPARγ, thereby reducing insulin resistance." (PMID 41170356, 2025). "The results of qRT-PCR showed that R7I upregulated the expression of the PPARγ gene and regulated lipid metabolism disorder." (PMID 41153866, 2025). "In ApoE−/− mice subjected to chronic mild stress, lipid metabolism disorders, increased adipocyte hypertrophy, and reduced PPARG gene expression promote AS, while PPARG exhibits an anti-ferroptosis effect." (PMID 40066336, 2025). "BYHWD activated the PPARγ pathway to induce peroxisome proliferation and regulated lipid metabolism disorders in the AD mice brain." (PMID 40195204, 2025). "We further determined the function of PPARγ which was upregulated by R7I during lipid metabolism disorder induced by Neisseria infection." (PMID 41153866, 2025). "For example, in our unpublished research, we found that PCOS mouse granulosa cells have PPARγ-dependent lipid metabolism disorders." (PMID 41321496, 2025). "Yue’s study demonstrated that PKP can improve lipid metabolism disorders by activating peroxisome proliferator-activated receptor gamma (PPARγ) in adipocytes and inhibiting the Toll-like receptor 4/nuclear factor kappa B (TLR4/NFκB) signaling pathway." (PMID 41001671, 2025). "The expression of PPARγ in muscles decreases with age, leading to carbohydrate-lipid metabolism disorders." (PMID 39894829, 2025). "A large number of literatures have reported that PPARγ play a key role in lipid metabolism disorder of AD." (PMID 40195204, 2025). "PPARγ is another key transcription factor; it is a nuclear receptor that can regulate lipid metabolism disorder by modulating free fatty acids." (PMID 35407014, 2022). "In agreement with previous studies, our study also showed that VOdipic-Cl improves liver lipid metabolism disorders by down-regulating the expression of PPARγ, C/EBPa, SREBP-1c and FAS proteins related to lipid synthesis." (PMID 35739990, 2022). "To explore the underlying mechanism behind TDQ's intervention in glucose and lipid metabolism disorder, we analyzed the gene and protein changes of PPARγ and DGAT2 expression in the livers." (PMID 31019978, 2019). "So far, several functional polysaccharides have been proven to reverse glucose and lipid metabolism disorders by upregulating the activity of nuclear receptor peroxisome proliferator-activated receptor gamma (PPARγ)." (PMID 30463189, 2018). "Several natural variants of PPARγ LBD, such as F360L, V290M, R357A, R397C, and P467L, have been associated with lipid metabolism disorders as well as cancer, e.g., Q286P, R288H." (PMID 28208577, 2017). "Genistein alleviated lipid metabolism disorder and decreased the mRNA and protein expression of PPARγ (P<0.05), and increased the protein expression of LC3II (P<0.05) in liver of HFD-fed rats." (PMID 27171397, 2016). "In addition, R7I regulated Neisseria-induced lipid metabolism disorder and inflammatory responses through activation of the PPARγ protein." (PMID 41153866, 2025).
lipid metabolism disorders (continued). "To further determined whether CG played a role in regulating lipid metabolism disorder by activating PPARγ receptor, we detected the expression of PPARγ protein and mRNA in cells of each group using western blotting and RT-PCR." (PMID 40195204, 2025). "In this study, we found that ZRH as a PPARγ activating medication can regulate inflammatory factors and adipokines, suppress lipid metabolism disorders and inflammation, enhance adipose tissue “brown,” increase AS plaque stability, and improve plasma lipidomic features." (PMID 41190023, 2025). "TDQ are, therefore, a potential Chinese medicinal formula that relieves IR and lipid metabolism disorder might be through promotion of PPARγ and decrease of DGAT2 expression." (PMID 31019978, 2019). "Further mechanistic study showed that amelioration of lipid metabolism disorder by FSH may be mediated at least in part by suppressing PPARγ expression and upregulating PPARα expression, and inhibiting inflammation in adipose tissues." (PMID 28248545, 2017). "Genistein treatment alleviated hepatic lipid metabolic disorder in HFD-fed rats that may be related to down-regulated PPARγ of liver." (PMID 27171397, 2016). "Lipidomics and molecular interlinking analyses indicated that the main pharmacodynamic substance, CG, present in BYHWD might activate the PPARγ pathway to induce peroxisome proliferation and regulate lipid metabolism disorders in the AD mice brain, thereby achieving therapeutic effects against AD." (PMID 40195204, 2025). "Furthermore, AD patients revealed lipid metabolism disorders characterized by excessive accumulation of long-chain fatty acids and elevated ceramide levels in the brain, along with diminished peroxisome count and decreased expression of PPARγ protein and mRNA." (PMID 40195204, 2025). "Furthermore, we speculated and detected several key transcription factors as the potential regulatory effects in lipid metabolic disorders, PPARα, PPARγ, and SREBP1, and found their aberrant expression in the PM2.5 exposure group." (PMID 37780625, 2023). "The reduction and inactivation of STAT3 lead to lipid metabolic disorders and promote triglyceride accumulation by upregulating the mRNA levels of ELOVL7, PPARG, MMP1, MMP13, and TIMP4, and downregulating the mRNA level of PTGS2." (PMID 39125712, 2024). "CIH mainly affected the transcription levels of the PPARγ, ACOX1, and UCP2 genes and further aggravated the HFD‐induced lipid metabolism disorders." (PMID 39229924, 2024). "For further verification of lipid metabolic disorders, an immunofluorescence technique was performed to analyze the expression of SREBP1 and PPARγ." (PMID 37780625, 2023). "These targets play an important role in the PPI network and KEGG signaling pathway, and they have a significant impact on glucose and lipid metabolism disorders and inflammation (such as TNF-α, AKT1, PPARG, and PTGS2)." (PMID 36199550, 2022). "These targets play an important role in the PPI network and KEGG signaling pathway, and they have a significant impact on glucose, lipid metabolism disorders, and inflammation (such as TNF-α, AKT1, PPARG, and PTGS2)." (PMID 36199550, 2022). "Our data reveal that both the PPARγ and estrogen receptor pathways play important roles in BPA-induced glucose and lipid metabolism disorders, but their modes of action are relatively independent." (PMID 32623698, 2021). "The results of differential metabolite enrichment analysis showed that ZRH could regulate glycerophospholipid metabolism and improve lipid metabolic disorders, which is consistent with the result that ZRH could upregulate PPARγ expression." (PMID 41190023, 2025). "Moreover, CACE can alleviate lipid metabolism disorder through inhibiting ER stress via PERK and ATF6 signaling pathways and activating PPARs with upregulating PPARα expression and downregulating PPARγ expression." (PMID 33688365, 2021).
lipid metabolism disorders (continued). "We demonstrated that long-term genistein treatment alleviated lipid metabolic disorder in HFD-fed adult male rats, this may be due to the regulation of PPARγ (a key gene of lipid metabolism) in liver; and autophagy machinery was not involved in these beneficial effects in STD- or HFD-fed rats." (PMID 27171397, 2016).
ischemia (42 papers, 2009 to 2025). A hypoperfusion of the BLOOD through an organ or tissue caused by a PATHOLOGIC CONSTRICTION or obstruction of its BLOOD VESSELS, or an absence of BLOOD CIRCULATION. "IRF6 acts as a PPARγ co-suppressor and directly binds to and suppresses PPARγ activity in murine cerebrovascular endothelial cells, eventually blocking PPARγ-mediated cerebrovascular endothelial cytoprotection following ischemia." (PMID 40235530, 2025). "The inhibition of PPARγ expression by translocator protein ligands inhibits IL‐4‐induced M2 polarization at the site of hypoxic ischemia in the brain." (PMID 39737788, 2025). "Hesperidin exhibits anti-apoptotic effects through activation of PPARγ, thereby ameliorating ischemia and reperfusion injury." (PMID 39052574, 2024). "In the case of ischemia, post-treatment with 1 μM amorfrutin B resulted in an increase in PPARG expression to 1.02-fold of the control." (PMID 38949694, 2024). "In another study, we also reported that KLF11 serves as a co-regulator of PPARγ to protect mice against ischemia-induced cerebrovascular injury." (PMID 36403074, 2022). "Previous studies have demonstrated that pioglitazone, a peroxisome proliferator-activated receptor gamma (PPARγ) agonist, inhibits ischemia-induced brain injury." (PMID 34208374, 2021). "In the current study, we found that the DNA-binding activity of PPARs was reduced by liver I/R injury, and this is consistent with a previous study that reported that ischemia results in a rapid decrease in the DNA binding of PPARγ." (PMID 34104311, 2021). "Recent studies indicate that PPARγ agonists attenuate ischemia-induced activation of microglia, expression of intracellular adhesion molecule 1 (ICAM-1), and neutrophil infiltration in C57BL/6 mice." (PMID 33281727, 2020). "Treatment with PGZ in the early phase post-ischemia appeared to exert beneficial effects through anti-apoptosis and anti-inflammatory response effects elicited by the expression of PPARγ." (PMID 29110250, 2018). "Recently, it has been shown that activation of Pparγ inhibited caspase-3 activity and protected murine cortical neurons against ischemia." (PMID 28357806, 2018). "This study is the first to report that IRF6 is a novel PPARγ co-suppressor that suppresses PPARγ-mediated cerebrovascular endothelial cytoprotection following ischemia." (PMID 28526834, 2017). "This study has identified IRF6’s role as a novel PPARγ co-suppressor that suppresses PPARγ-mediated cerebrovascular endothelial cytoprotection following ischemia." (PMID 28526834, 2017). "Altogether these results suggest that HHcy exerts its myopathic effects via reduction of the PGC-1α/PPARγ axis after ischemia." (PMID 25608649, 2015). "Altogether these results suggest that HHcy exerts its myopathic effects via reduction of the PGC-1/PPARγ axis after ischemia." (PMID 25608649, 2015). "Beneficial effects of PPARγ activators were investigated in mice models subjected to damage for ischemia." (PMID 25246934, 2014). "In murine models, IRF6 expression in cerebrovascular endothelial cells has been shown to promote PPARγ-related cytoprotection following ischemia, suggesting that disruption of IRF6 may impair these protective pathways." (PMID 40149423, 2025). "In response to ischemic conditions, the PPARγ protein expression level increased from 0.0095 pg to 0.0175 pg (84% increase), and exposure to amorfrutin B decreased the PPARγ level to 0.014 pg (20% decrease compared to ischemia)." (PMID 34440058, 2021). "In this study, we demonstrate for the first time that amorfrutin B, a selective modulator of peroxisome proliferator-activated receptor gamma—PPARγ, can protect brain neurons from hypoxia- and ischemia-induced degeneration when applied at 6 h post-treatment in primary cultures." (PMID 34440058, 2021). "Agonists of PPARγ have been used to reduce neurodegenerative changes in mouse models of neurodegenerative diseases and have also shown benefits in experimental models of stroke and ischemia." (PMID 28357806, 2018).